HIF3A (hypoxia inducible factor 3 subunit alpha)
Diseases named in the same sentence as HIF3A in open-access papers (continued):
Sharing a sentence is not in itself a finding about the gene and the disease.
Cerebral ischemia (1 paper, 2025). Restriction of arterial blood supply to the brain associated with insufficient oxygenation to support the metabolic requirements of the tissue. "We explain this effect from the perspective of its impact on the GSH-dependent pathways of endogenous neuroprotection and the increased expression of mRNA for HSP70, HIF-1α, and HIF-3α under conditions of acute experimental cerebral ischemia, as well as the enhancement of glutathione synthesis." (PMID 40299680, 2025).
cervical cancer (1 paper, 2022). A primary or metastatic malignant neoplasm involving the cervix. "In the current study, we investigated the regulatory loop among HIFs (HIF-1α and HIF-3α) and miR-630 to identify their functions in cervical cancer progression." (PMID 36277475, 2022). "The newly identified functions of HIF-3α and its regulatory loop with miR-630 in HeLa cells also provide theoretical basis for future clinical prognosis and treatment of cervical cancer." (PMID 36277475, 2022). "The discovery highlights the regulatory functions of HIF-3α and miR-630 and identifies new therapeutic candidates for hypoxia and radiotherapy strategies to treat cervical cancer." (PMID 36277475, 2022). "Higher expression of HIF1A and HIF3A could shorten the survival time of cervical cancer patients, indicating their oncogenic functions." (PMID 36277475, 2022). "However, it remains largely unknown how HIF-3α functions in cervical cancer." (PMID 36277475, 2022).
chronic periodontitis (1 paper, 2021). A chronic inflammatory process that affects the tissues that surround and support the teeth. "Previous researches revealed that HIF3A expression is increased in periodontitis and in LPS-treated BV-2 microglial cells." (PMID 33604388, 2021).
Cognitive impairment (1 paper, 2021). Abnormal cognition is characterized by deficits in thinking, reasoning, or remembering. "However, the function and mechanism of Hif3a in the pathogenesis of high glucose-induced cognitive deficits is still unknown, and further research is needed." (PMID 34975464, 2021).
colon cancer (1 paper, 2024). "In addition, the B-RAF- and KRAS-driven colon cancer cells used in our analyses were “addicted to autophagy” because they overexpressed the hypoxia-inducible factors HIF-1α, HIF-2α, and HIF-3α, which promote autophagy." (PMID 38473963, 2024).
colorectal tumors (1 paper, 2016). "This study demonstrates that HIF-3α is overexpressed in both mouse and human colorectal tumors, and predicts poor prognosis." (PMID 26871465, 2016). "Together, these data suggest that HIF-3α is important in colorectal tumor development and cancer progression." (PMID 26871465, 2016). "Here we found that HIF-3α protein was increased in colorectal tumors from both mouse models and human patients." (PMID 26871465, 2016). "In addition, colorectal tumors isolated from patients demonstrated an increase in HIF-3α compared to their adjacent normal tissue." (PMID 26871465, 2016).
edema (1 paper, 2025). An abnormal accumulation of fluid beneath the skin, or in one or more cavities of the body. "Heparin precisely targets this pathway by upregulating Epsa1, restoring Idh2 activity, and stabilizing Hif3a, thereby enhancing Pink1/Parkin-mediated mitophagy to eliminate impaired mitochondria, suppress sustained inflammatory activation, and ultimately reduce neuronal apoptosis and cerebral edema." (PMID 41585220, 2025).
emphysema (1 paper, 2024). "We noticed that HIF-3α mRNA levels were upregulated up to the pre-COPD stage (patients with emphysema but no airflow limitation)." (PMID 39310101, 2024). "Although systemic hypoxia and severe emphysema are seen in COPD, the mechanisms underlying hypoxia, especially HIF-3α and emphysema in COPD have not been investigated." (PMID 39310101, 2024).
endometrial cancer (1 paper, 2019). Primary or metastatic malignant neoplasm involving the endometrium (mucous membrane that lines the endometrial cavity). "While high expression of HIF3A in endometrial cancer has been correlated with poor outcomes, its functional role remains to be elucidated in relation to PCa." (PMID 30866497, 2019).
endotoxemia (1 paper, 2025). "This suggests that chronic hypoxia and HIF-3α exert an inflammatory dampening response to endotoxemia that is dependent on microglia responses." (PMID 39940901, 2025).
erythrocytosis (1 paper, 2021). "Two variants of the HIF3A gene were associated with familial erythrocytosis in human." (PMID 34090336, 2021).
idiopathic pulmonary fibrosis (1 paper, 2020). Idiopathic pulmonary fibrosis (IPF) is a nonneoplastic pulmonary disease that is characterized by the formation of scar tissue within the lungs in the absence of any known cause. "For example, we show this complex relationship between the different members of HIF in idiopathic pulmonary fibrosis, where lack of HIF-3α in HIF response, by its particular hypermethylation, is associated with an increase in cell differentiation." (PMID 33149807, 2020).
liposarcoma (1 paper, 2025). A usually painless malignant tumor that arises from adipose tissue. "In liposarcoma, miR-210-3p and miR-485-5p were shown to target and inhibit HIF-3α expression in vitro to downregulate the oncogenic hypoxic-signalling activities, suggesting these two miRNAs could play tumour-inhibiting role in liposarcoma." (PMID 39736850, 2025).
lung adenocarcinoma (1 paper, 2025). A carcinoma that arises from the lung and is characterized by the presence of malignant glandular epithelial cells. "A possible explanation for this is the reciprocal regulation between PER1 and HIF1α, a potential role for HIF3α, or that hypoxia has context specific roles in molecular subsets of lung adenocarcinoma." (PMID 40715535, 2025).
lung disorder (1 paper, 2024). A disease involving the lung. "In the present study, however, expression of HIF-1α and HIF-2α were unaffected in HIF3A gene-disrupted mice compared to the WT mice, suggesting that the lung disorder of HIF3A gene-disrupted mice is not caused by a mechanism mediated by HIF-1α or HIF-2α." (PMID 38717999, 2024).
major depressive disorder (1 paper, 2016). An episode of depression lasting two or more weeks without an intervening episode of mania. "Further examples include the hypoxia inducible factor 3 alpha subunit (Hif3a), whose expression was found to be increased in schizophrenic and bipolar patients or Sgk1 and Tsc22d3, which were associated with high interleukin (IL)-6 levels in patients suffering from the major depressive disorder." (PMID 27188165, 2016).
melanoma (1 paper, 2023). A malignant, usually aggressive tumor composed of atypical, neoplastic melanocytes. "For instance, MEF2A, EMP2, ZNF440, PIGL, FRMD4B, and HIF3A are not only downregulated in TCGA-SKCM melanoma samples but also essential for restraining tumor growth in CRIPSR KO screens." (PMID 37904237, 2023).
myeloma (1 paper, 2014). "Therefore, we suggest that let-7a might promote myeloma angiogenesis by inhibiting its target (i.e. HIF-3α) and subsequently triggering VEGF expression." (PMID 24886719, 2014).
Neurodegeneration (1 paper, 2021). Progressive loss of neural cells and tissue. "Due to the fact that T2D and neurodegeneration disease shared the overlapping pathophysiological mechanisms and pathways, we detected Mmp8 and Hif3α mRNA expression value in AD and PD samples by analyzing gene expression datasets in GEO." (PMID 34975464, 2021).
osteoarthritis (1 paper, 2018). A noninflammatory degenerative joint disease occurring chiefly in older persons, characterized by degeneration of the articular cartilage, hypertrophy of bone at the margins and changes in the synovial membrane. "Targeting of HIF-3α by miR-210 results in increasing chondrocyte proliferation and prompts the extracellular matrix deposition on osteoarthritis." (PMID 29953500, 2018).
pituitary tumor (1 paper, 2019). A benign or malignant neoplasm affecting the pituitary gland. "In addition, we looked at genes that were not previously investigated in pituitary tumors, FAM163A, HIF3A, and PRSS8, which were hypermethylated in NFPAs." (PMID 31731486, 2019).
prostate tumor (1 paper, 2014). "The role of HIF3α isoforms in the hypoxic induction of the pro-inflammatory transcriptoma of prostate tumor cells is still unknown." (PMID 24801981, 2014). "HIF3α regulation was cell specific and its expression was limited to DU145 cells among the prostate tumor models examined." (PMID 24801981, 2014).
respiratory failure (1 paper, 2013). The significant impairment of gas exchange within the lungs resulting in hypoxia, hypercarbia, or both, to the extent that organ tissue perfusion is severely compromised. "Recent findings showed that depletion of cells with CCSP promoter activity was associated with alveolar hypoplasia and respiratory failure, adding to the idea that Ccsp downregulation as a result of Hif3α-mediated Foxp2 upregulation, directly leads to reduced numbers of Clara cells." (PMID 23451260, 2013).
rheumatoid arthritis (1 paper, 2022). A chronic, systemic autoimmune disorder characterized by inflammation in the synovial membranes and articular surfaces. "HIF-α has three isoforms (HIF-1α, HIF-2α, HIF-3α), and it has been reported that HIF-2α is mainly expressed in FLSs in the joint cavity of patients with rheumatoid arthritis." (PMID 35366946, 2022).
sarcoma (1 paper, 2014). A usually aggressive malignant neoplasm of the soft tissue or bone. "We showed that HIF3α transcripts, expressing a 3’UTR containing the miR-485-5p and miR-210-3p target sites, are expressed in all sarcoma cell lines and upregulated upon hypoxia." (PMID 24927770, 2014).
Stroke (1 paper, 2025). Sudden impairment of blood flow to a part of the brain due to occlusion or rupture of an artery to the brain. "Our findings underscore Hif3α’s role in AD progression, and suggest shared risk pathways with stroke, emphasizing Hif3α as a potential therapeutic target." (PMID 40243952, 2025). "However, current research on Hif3α’s role in brain health primarily focuses on stroke rather than neurodegenerative diseases." (PMID 40243952, 2025).
tumor (33 papers, 2012 to 2026). "Several previous studies revealed that the longer HIF-3α variants can promote tumor growth or metastasis in colorectal and pancreatic cancers, suggesting HIF-3α inhibitors might be beneficial for certain tumors." (PMID 35534502, 2022). "However, upregulation of long HIF-3α variants has been frequently observed in various cancer cell lines and may induce the expression of genes involved in tumor progression or aggressiveness [for review, see]." (PMID 38020884, 2023). "We analyzed the mRNA expression levels of major proangiogenic molecules on the tumor surface and tumor depth, namely HIF1α, HIF2α, HIF3α, VEGF-A, VEGFR1, VEGFR2, and ETS-1." (PMID 41359448, 2026). "RBX1 is a component of the VHL tumor suppressor complex, which ubiquitinates HIFα subunits (HIF1α, HIF2α, and HIF3α) and targets them for degradation under normoxic conditions." (PMID 40436847, 2025). "HIF-3α is a molecule that was massively found to be silenced in 78.3% of the tumor samples (RQ < 0.5)." (PMID 38607072, 2024). "DNA methylation analysis also revealed the methylation of multiple genes (FRMD6-AS2, SESN3, CYTL1, MIR4429, HIF3A, and ATP1B2) associated with tumor growth suppression." (PMID 36975488, 2023). "The observed change in the expression of these genes thus suggests a possible role of HIF3A in maintaining the neuroepithelial phenotype of tumor cells." (PMID 35803925, 2022). "Since the physiological functions of HIF-3α (especially its complicated relationship with the other isoforms) have not been fully revealed, more investigations are urgently needed to evaluate the strategy of targeting HIF-3α in tumor and other diseases." (PMID 35534502, 2022). "Here, the LUAD patients showed a significantly moderate positive relationship between plasma and tumor tissues for HIF3A expression (r = 0.493, p < 0.001)." (PMID 34245041, 2021). "Overall, the results demonstrated that HIF3A expression levels in both groups were significantly lower in tumor tissues than in adjacent normal tissues (p < 0.05)." (PMID 34245041, 2021). "In this context, HIF3A expression showed higher detection efficiency in LUAD tumor tissues than in LUSC patients." (PMID 34245041, 2021). "Bioinformatics tools were used to analyze HIF3A expression between tumor tissues and their adjacent normal tissues in LUAD and LUSC patients via signature score analysis (GEPIA 2)." (PMID 34245041, 2021). "The efficacy of detection of HIF3A was reported using the ROC‐AUC phenomenon in the tumor tissues and plasma samples of LUAD and LUCS patients." (PMID 34245041, 2021). "The clinical significance of HIF3A was evaluated in the plasma and tumor tissues using the receiver operating curve (ROC) and the area under the curve (AUC)." (PMID 34245041, 2021). "We investigated HIF3A mRNA expression in the plasma and tumor tissues of patients with NSCLC and explored its clinical significance." (PMID 34245041, 2021). "The correlation between plasma and tumor tissues with respect to HIF3A expression in 58 LUAD and 62 LUSC patients is shown by scatter plots." (PMID 34245041, 2021). "The current study aimed to evaluate HIF3A mRNA expression in the plasma and tumor tissues of patients with LUAD and LUSC." (PMID 34245041, 2021). "Overall, the plasma and tumor tissues of NSCLC patients demonstrated notable efficacies for the diverse detection of HIF3A mRNA." (PMID 34245041, 2021). "HIF3A expression was notably downregulated in the plasma or tumor tissues of LUAD and LUSC patients compared with the plasma of the healthy control group or adjacent tumor tissues." (PMID 34245041, 2021). "HIF3A expression was evenly distributed in the different tumor zones, while HIF1A, HIF2A, and ARNT expressions were enriched in the perinecrotic zones and/or in blood vessels of the tumor (Online Resource 9)." (PMID 29149419, 2018). "HIF-3α expression was further assessed in the normal and tumor tissues of VhlΔIE/Apcmin/+ and VhlF/F/Apcmin/+ mice." (PMID 26871465, 2016).
tumor (continued). "Both HIF2α and HIF3α appear expressed in a cell-specific manner and play non redundant roles in adapting to hypoxia and in hypoxic tumor growth and progression." (PMID 24801981, 2014). "We therefore characterized the nuclear expression profile of HIF1α, HIF2α and HIF3α in the tumor prostate cell lines LNCaP, DU145 and PC3 following oxygen deprivation." (PMID 24801981, 2014). "A zebrafish gene related to the hypoxia-induced factor (HIF)-3α was strongly up-regulated, and the liver-specific tumor suppressor, C/EBP alpha was strongly down-regulated." (PMID 23936019, 2013). "In the peritumoral mucosa samples, we saw a statistically significant rise in the expression levels of HIF-3α when compared to the paired tumor samples (Wilcoxon test, p = 0.006, z = 2.75) despite this still largely downregulated (55%) in relation to the paired control samples (RQ < 0.5)." (PMID 38607072, 2024). "The expression levels of Epas1 and Vegf mRNA in the tumor tissue of the TH mice were lower in comparison with the control group, while the levels of Hif1a, Epas1, and Hif3a mRNA expression in the peritumoral area were statistically significantly higher relative to the tumor tissue." (PMID 39063041, 2024). "This was confirmed via the Hif3a isoform, which is expressed during long-term hypoxic exposure (more than 12 h) and remains active for a long time after, which was typical for the tumor tissue." (PMID 39063041, 2024). "Higher Hif3a and Vegf expression in the tumors of the SH mice in comparison with the TH mice may indicate a later stage of tumor progression." (PMID 39063041, 2024). "Additionally, the methylation of FRMD6-AS2, SESN3, CYTL1, MIR4429, HIF3A, and ATP1B2, which are associated with tumor growth suppression, was detected by DNA methylation analysis." (PMID 36975488, 2023). "In addition, the methylation of FRMD6-AS2, SESN3, CYTL1, MIR4429, HIF3A, and ATP1B2, which are associated with tumor growth suppression, was also detected." (PMID 36975488, 2023). "Furthermore, HIF3A expression had a significant positive correlation in the plasma and tumor tissues of LUAD and LUSC patients." (PMID 34245041, 2021). "Furthermore, in 58 patients with LUAD, the tumor tissues had significantly low expression of HIF3A mRNA." (PMID 34245041, 2021). "Therefore, the expression level of HIF3A was directly correlated between the plasma and tumor tissues of NSCLC patients." (PMID 34245041, 2021). "Thus, HIF3A expression was not only correlated with plasma and tumor tissues, but also showed potential significance in NSCLC." (PMID 34245041, 2021). "Thus, HIF3A expression was significantly downregulated in the tumor tissues or plasma samples of NSCLC patients." (PMID 34245041, 2021). "In cancer cells, is HIF3α involved in neoangiogenesis to sustain tumour growth?" (PMID 29643458, 2018). "Furthermore, the Vhl knockout mouse model (VhlΔIE/Apcmin/+) demonstrates an increase in HIF-3α expression in both normal and tumor tissue samples." (PMID 26871465, 2016). "Based on our results, miR-210-3p promotes survival of GBM cells in the tumor microenvironment, promotes aggressiveness by imparting temozolomide resistance and targets HIF3A, which is known to function as a negative regulator of hypoxia-inducible gene expression." (PMID 25129238, 2014). "Additionally, HIF-1α and HIF-2α drive angiogenesis during tumour development, whereas HIF-3α negatively regulates the HIF pathway in vascular cells by decreasing hypoxia-mediated VEGF expression." (PMID 24886719, 2014). "Thus, our study may indicate that HIF3A could be involved in tumor formation, occurrence, and progression of NSCLC, and subsequent studies are needed to fully understand and evaluate this hypothesis." (PMID 34245041, 2021). "HIF3A may be involved in hypoxic responses during tumor occurrence and development." (PMID 34245041, 2021). "HIF-1α, HIF-2α, and HIF-3α H-expression levels in relation to tumor grade, TNM stage, and tumor size in 150 patients with ccRCC." (PMID 38571885, 2024).